POSTN (periostin)
Diseases named in the same sentence as POSTN in open-access papers (continued):
Sharing a sentence is not in itself a finding about the gene and the disease.
lymph node metastasis (28 papers, 2012 to 2026). "Based on data from the literature, periostin is increasingly recognized as the molecule associated with poor prognosis, aggression of the histological grade, lymph node metastasis, distant metastasis and TNM stage of CRC." (PMID 35056404, 2022). "Among these proteins, periostin was used for further study, and the over-expression of periostin was associated with advanced clinical stage lymph node metastasis and decreased overall survival in NPC." (PMID 26184160, 2015). "Furthermore, a high expression of POSTN was strongly associated with lymph-node metastasis, tumor differentiation, venous infiltration, tumor progression, and angiogenesis." (PMID 39272978, 2024). "Upregulation of periostin-introduced invasion and lymph node metastasis may be due to loss of cellular polarity/cohesiveness and epithelial–mesenchymal transition (EMT)." (PMID 36120433, 2022). "POSTN was found to be associated with lymph node metastasis (p = 0.018)." (PMID 26857387, 2016). "In CAFs, high periostin expression was significantly correlated with high Smad2/3 expression, increased invasion depth, lymph node metastasis, venous invasion, advanced disease stage, and a higher rate of relapse." (PMID 39941916, 2025). "The periostin-positive stroma group was significantly correlated with a high T-stage (p = 0.011), lymph node metastasis (p = 0.011), venous invasion (p = 0.006), a high relapse rate (p = 0.015), and a high advanced stage (p = 0.015)." (PMID 39941916, 2025). "The results showed that circ‐POSTN expression was associated with TNM grade, lymph node metastasis, and tumor size." (PMID 38553795, 2024). "Considering cancer-specific survival, Cox univariate analysis indicated that a pT category ≥ 3, LVI, concomitant subtype histology, pathological lymph node metastasis, high budding, and high stromal periostin expression were poor prognostic predictors." (PMID 35850759, 2022). "LVI and lymph node metastasis were detected in 38 (69%) and eight (15%) cases with high stromal periostin expression and in 18 (25%) and two (3%) cases with low stromal periostin expression, respectively." (PMID 35850759, 2022). "POSTN was also found to be increasingly expressed in lymph node metastasis, especially in N0 and N1 in LUSC and N0, N1, and N2 in LUAD." (PMID 35508298, 2022). "POSTN is significantly downregulated in gastric cancer, and it can be used as a predictor of lymph node metastasis in such patients." (PMID 35508298, 2022). "The overexpression of POSTN is related to the clinical stage, degree of malignancy, lymph node metastasis, and OS in NSCLC patients, and it is also an independent risk factor for OS in NSCLC patients." (PMID 35281822, 2022). "In this study, we identified a specific periostin+CAF subset that promoted lymph node metastasis (LNM) in cervical squamous cell carcinoma (CSCC)." (PMID 33124726, 2021). "POSTN expression in CAFs was significantly higher in the group of patients with lymph node metastasis (N2) than the one with N0 in the whole study cohort and the AC group (** p < 0.005 in both cases, Mann–Whitney U test)." (PMID 32987711, 2020). "In the present study, survival times were better for the low-periostin group than the high-periostin group, even for patients with lymph-node metastasis." (PMID 30131847, 2018). "Positive periostin expression in cancer cells was observed in 334 (30.76%) of the 1,086 breast cases and correlated with tumor size, histological grade, lymph node metastasis, triple-negative breast cancer, and postoperative distant metastasis." (PMID 29161296, 2017). "We found that lymph nodes metastasis (p < 0.001) and POSTN expression (p = 0.044) were prognostic factors for overall survival rates." (PMID 26023718, 2015). "The percentage of periostin-positive cases increased with the stage of progression and with lymph node metastasis." (PMID 22952986, 2012).
lymph node metastasis (continued). "On the other hand, previous immunohistochemical studies showed a possible correlation between periostin expression and lymph node metastasis in cancer cases." (PMID 22952986, 2012). "After multivariate analysis, age, histological grade, lymph node metastasis, tumor size, triple-negative breast cancer, and periostin expression were related to post-operative distant metastasis (P = 0.01, 0.001, 0.001, 0.035, 0.001, and 0.001, respectively)." (PMID 23056395, 2012). "Among these clinicopathologic factors, the multivariate analysis revealed that periostin in CAFs-positive expression (p < 0.001), age ≥ 65 years (p = 0.006), poorer differentiation (p = 0.001), and lymph node metastasis (p = 0.019) were significantly correlated with poor survival." (PMID 39941916, 2025). "Patients were categorized into high and low POSTN expression groups, which revealed significant associations with tumor differentiation (P = 0.006), TNM stage (P < 0.001), tumor size (P = 0.006), lymph node metastasis (P < 0.001), vascular invasion (P = 0.003), and distant metastasis (P = 0.002)." (PMID 40520021, 2025). "In addition, high level of POSTN was positively related to lymph node metastases and the TNM stages." (PMID 35508298, 2022). "Higher expression of POSTN was observed in HNC tissues of the patients with lymph node metastasis, confirming that overexpression of POSTN might contribute to tumor malignancy, especially the metastatic potential." (PMID 26857387, 2016). "Notably, periostin was enriched in exosomes secreted from metastatic compared to non-metastatic cell lines and in plasma samples from patients with lymph node metastasis." (PMID 27589561, 2016). "After universal analysis, periostin was observed to be related to tumor size, histological grade, lymph node metastasis, postoperative distant metastasis, triple-negative breast cancer, and CSC ratio (P = 0.01, 0.003, 0.001, 0.001, 0.001, and 0.001 respectively)." (PMID 23056395, 2012). "After universal and Spearman regression correlation analysis, periostin was observed to be related to histological grade, CSC ratio, lymph node metastasis, tumor size, and triple-negative breast cancer (all P<0.05)." (PMID 23056395, 2012). "POSTN was predominantly expressed in fibroblasts across independent non-small cell lung cancer datasets and was elevated in LUAD tissues, tissue-derived exosomes, and serum exosomes, correlating with advanced stage, lymph node metastasis, and poor survival." (PMID 42238572, 2026). "In the present study, high stromal periostin expression was associated with non-papillary gross findings, higher pT category, LVI, concomitant carcinoma in situ, subtype histology, lymph node metastasis, positive surgical margins, high tumor budding, and high TAICs." (PMID 35850759, 2022). "Cox univariate analysis showed that pT category ≥ 3, LVI, pathological lymph node metastasis (positive vs. negative/no lymph node dissection), positive surgical margins, high budding, and high stromal periostin expression were correlated with lower overall survival." (PMID 35850759, 2022). "Furthermore, the serum levels of periostin were obviously higher in patients with lymph node metastases than those without (P = 0.012)." (PMID 27816968, 2017). "POSTN levels were significantly correlated with TNM stages, lymph node metastasis, distant metastasis of BCa patients, but not with age and molecular subtypes." (PMID 38504252, 2024).
Myocardial fibrosis (28 papers, 2013 to 2026). "Myocardial fibrosis in these rats is linked to TGFβ activation, and TGFβ1 can induce POSTN expression in cardiac and vascular cells." (PMID 40606601, 2025). "The current histopathological and immunohistochemical study focuses on the ECM protein periostin (POSTN) at tissue level and its correlation with myocardial fibrosis and other hallmark histopathological characteristics of HCM." (PMID 37939043, 2023). "In neonatal periostin-knockout mice subjected to MI, myocardial fibrosis persisted for up to 3 weeks after injury." (PMID 41191311, 2026). "Active CMFs are proliferative and contribute to the production of extracellular matrix and matricellular proteins such as periostin, to myocardial fibrosis, and thus to muscle stiffness." (PMID 40267335, 2025). "Studies have shown that the upregulation of POSTN expression in human failing hearts is related to myocardial fibrosis." (PMID 40606601, 2025). "Recent publications have reported the fibrogenic role of Periostin, demonstrating the significant effect of Periostin-expressing subset of cardiac fibroblasts on myocardial fibrosis." (PMID 38216590, 2024). "Runx1 expression was also observed in cardiac fibroblasts along with genes contributing to myocardial fibrosis, such as POSTN, MEOX1 and FAP, and its expression was also negatively correlated to ejection fraction." (PMID 38862712, 2024). "We have also shown that myocardial gal3 expression closely follows the expression of other molecules representing myocardial fibrosis, such as periostin." (PMID 37174619, 2023). "POSTN expression is upregulated and positively correlated with myocardial fibrosis in heart failure patients." (PMID 37939043, 2023). "Although the role of periostin in cardiac injury and myocardial fibrosis has been widely studied, the potential impact of periostin in DCM had been unexplored." (PMID 37993768, 2023). "In previous reports, Periostin expression induced by oxidative stress contributes to myocardial fibrosis in high salt-induced hypertension model." (PMID 36359784, 2022). "In human failing hearts, cardiac periostin positively correlated with the degree of myocardial fibrosis as well as with left ventricular diastolic dimension." (PMID 36369212, 2022). "Periostin is involved in matrix remodelling across health and disease, and increased levels of periostin are reported in pulmonary and myocardial fibrosis." (PMID 34271169, 2021). "POSTN is critical in cardiac development and remodeling, and the expression was found to be consistent with the percentage of myocardial fibrosis." (PMID 31902369, 2020). "In mice with MI for 4 weeks, masson’s trichrome staining indicated that myocardial fibrosis area (fibrotic length/LV circumference) was markedly lower in periostin knockout mice than in wildtype mice." (PMID 29872491, 2018). "Increased ROS production, activation of ERK/TGF-β/periostin pathway and myocardial fibrosis are important events in DCM." (PMID 26750922, 2016). "Alleviated ROS genesis by resveratrol prevents myocardial fibrosis by regulating periostin related signaling pathway." (PMID 26750922, 2016). "Considering the relationship between TGF-β and periostin, we postulate that activation of ERK/TGF-β/periostin pathway by oxidative stress is, in part, a key event in the development of myocardial fibrosis in DCM." (PMID 26750922, 2016). "Periostin plays an important role in cardiac development and remodelling and its distribution and expression are consistent with the extent of myocardial fibrosis." (PMID 26249143, 2015). "Previous studies had demonstrated the pathophysiological role of periostin in myocardial fibrosis and cardiac remodeling in vivo and in vitro." (PMID 26281830, 2015). "In contrast, 12 weeks after implantation, there was little difference in the degree of myocardial fibrosis between the control and the periostin peptide-treated animals." (PMID 23700403, 2013).
Myocardial fibrosis (continued). "However, periostin has been shown to recruit activated fibroblasts in mice and to increase myocardial fibrosis after experimental MI in swine, which limits its potential to promote heart regeneration." (PMID 41191311, 2026). "Third, the mechanism of progression of myocardial fibrosis induced by periostin is still uncertain." (PMID 35318760, 2022). "Oxidative stress-induced periostin is involved in myocardial fibrosis and hypertrophy." (PMID 34383711, 2021). "The role of periostin in myocardial fibrosis in adult animals remains controversial." (PMID 29872491, 2018). "The effects of periostin on cardiomyocyte contractility are unknown, but periostin does play a role in myocardial fibrosis and hypertrophy." (PMID 29695980, 2018). "Here we show that periostin is involved in myocardial fibrosis in STZ-induced type 1 diabetic mice." (PMID 26750922, 2016). "Our results suggest that ROS/ERK/TGF-β/periostin pathway may contribute to myocardial fibrosis in DCM and resveratrol has a therapeutic potential in ameliorating these processes." (PMID 26750922, 2016). "Because the product of the periostin gene is required for the development of chronic myocardial fibrosis, we determined whether the administration of recombinant periostin peptide would be sufficient to induce myocardial fibrosis." (PMID 23700403, 2013). "However, periostin peptide treatment increased myocardial fibrosis in the remote region at one week and 12 weeks post-treatment." (PMID 23700403, 2013). "As POSTN reportedly plays a vital role in the cardiac vicious cycle (aging-fibrosis-inflammation-aging) by simultaneously promoting myocardial fibrosis and cardiac fibroblast aging, POSTN may also play a significant role in promoting inflammation through tissue aging." (PMID 38020106, 2023). "Thus, this study was designed to test whether activation of TGF-β/periostin pathway is associated with myocardial fibrosis of DCM in STZ-induced diabetic mice and to evaluate whether resveratrol ameliorates fibrogenesis by modulating ROS/ERK/TGF-β/periostin pathway in vivo and in vitro." (PMID 26750922, 2016). "The product of the periostin gene is required for myocardial fibrosis, but over expressing it is not sufficient." (PMID 23700403, 2013). "Our current study shows a direct correlation between circulating periostin levels in SSc patients and several echocardiography parameters related to the mass and size of the left ventricle, including LV mass, LV mass index, and LVEDD that can reflect myocardial fibrosis and ventricular remodeling." (PMID 36369212, 2022).
fibrosis (26 papers, 2016 to 2026). the formation of excess fibrous connective tissue in an organ or tissue in a reparative or reactive process. "Conversely, pcy mice deficient for periostin are protected and exhibit a decrease kidney mass and cystic index, a reduced extent of fibrosis and increase life span." (PMID 38039285, 2023). "Periostin combined with DNA aptamer successfully inhibited tubulointerstitial fibrosis induced high expression of periostin, and the effects of glucose at 22 mmol/L and TGF‐β1 at 10 ng/mL were significant." (PMID 39570100, 2024). "Since knockout of POSTN alone has been shown to ameliorate deterioration of kidney fibrosis, reduction of POSTN‐dependent fibrosis in Stab‐POSTN‐TrKO mice is a likely explanation for this observation." (PMID 37357460, 2023). "Urinary periostin/creatinine values were elevated in patients with fibrosis and tubular atrophy, and in those who developed progressive kidney disease." (PMID 33123151, 2020). "POSTN is directly attached to collagen type I, V, fibronectin, tenascin-C, and POSTN itself and this complex assists in subepithelial fibrosis and tissue remodeling." (PMID 30061580, 2018). "Inhibition of periostin or αv integrin prevented the development or progression of allergen-induced skin inflammations, including fibrosis." (PMID 28219384, 2017). "QSYQ alleviates cardiac fibrosis and hypertrophy in Dahl Salt-sensitive hypertension rats in vivo and angiotensin II-induced cardiac organoids in vitro via regulating multiple signaling pathway activator periostin." (PMID 40606601, 2025). "Regarding whether periostin may represent an early marker of cardiac involvement in SSc, future longitudinal analysis will be necessary to determine whether elevated serum periostin levels precede or follow fibrosis and cardiac disease." (PMID 40743121, 2025). "Indeed, mice with interstitial fibrosis and increased microalbuminuria presented a strong periostin staining in areas with fibrosis and vessels; tubules were the most predominant location for periostin staining." (PMID 35883655, 2022). "Moreover, key mediators of cardiac fibrosis, periostin and TGFβ, were increased in AngII-treated NO-GC1 KOs compared to WT, with the TGFβ mRNA being higher in the NO-GC1 KOs already under non-treated conditions." (PMID 33171621, 2020). "Fibrosis is a complex condition mediated by profibrotic factors, an imbalance of collagen synthesis and degradation, upregulation of the extracellular matrix including POSTN and TNC, and increased oxidative stress." (PMID 30186543, 2018). "Similarly, in the DDC-induced fibrosis model, Periostin KO mice exhibited reduced liver fibrosis." (PMID 38216590, 2024). "Specifically, both periostin and YKL-40 have been suggested to be involved in the development of airway fibrosis and remodeling." (PMID 39534447, 2024). "Periostin and human chitinase-3-like protein 1 (YKL-40) have been suggested to be involved in the development of airway fibrosis and remodeling." (PMID 39534447, 2024). "Both periostin and TNC bind to each other and also co-localize in subepithelial fibrosis in asthmatic patients." (PMID 30473714, 2018). "Because periostin can increase MMP9 expression, but also aggravates cyst growth and fibrosis in pcy mouse cystic kidneys, we first ask whether its expression could be modified in the Nek8jck (jck) model." (PMID 38039285, 2023). "A previous investigation into the aspergillus fumigatus antigen-challenged mice model supported that periostin serves a beneficial role in protesting AHR, serum IgE levels, and outcome of peribronchial fibrosis by intensifying TGF-β-mediated Treg differentiation." (PMID 36611844, 2022). "The treatment of animals with periostin patches (lacking the N-terminal signal peptide and C-terminal region) not only perfected cardiac fraction and ejection fraction but also contained fibrosis after MI." (PMID 36611844, 2022).
fibrosis (continued). "However, unlike adult TazPM♂, juvenile TazPM♂ hearts do not yet have any detectable cardiac fibrosis, elevated Nppa/Bmp10, or abnormal periostin or lipid deposition evident." (PMID 39125771, 2024). "The increased cardiac fibrosis induced by MI was paralleled by significantly increased expression of the pro-fibrotic genes, connective tissue-derived growth factor (CTGF), periostin and fibronectin; expression of matrix metalloproteinase (MMP)-9 also tended to increase in WT (P = 0.05)." (PMID 29192208, 2017).